ATRX (ATRX chromatin remodeler)
Diseases named in the same sentence as ATRX in open-access papers (continued):
Sharing a sentence is not in itself a finding about the gene and the disease.
cancer (continued). "In particular ATRX loss is intimately linked to the alternative lengthening of telomeres (ALT), a mechanism that contributes to cellular immortality in cancer, genetic instability and increased mutational rate." (PMID 32751892, 2020). "Several ERGs had the highest mutation frequency repeatedly in many cancer types, namely the KMT2C/D family (seven cancers), ARID1A (five cancers), BAP1 (three cancers), and ATRX (three cancers)." (PMID 32963031, 2020). "The association of ATRX mutation and ALT17,22, for instance, is now extensively described and provides a vehicle to telomerase-independent immortalization in affected cancer cells." (PMID 30808951, 2019). "Although genetic mutations in ATRX and DAXX are often demonstrated in ALT positive cancers, a fraction of cancers display significant defects in DAXX/ATRX protein expression and/or function that do not stem from genetic mutations." (PMID 30214690, 2018). "There is a strong correlation between genetic mutations in ATRX/DAXX/H3.3 and cancers that rely on the ALT pathway for telomere maintenance." (PMID 30214690, 2018). "In cancers, ATRX loss and ALT are tightly linked, implicating ATRX as a suppressor of the ALT pathway." (PMID 30226859, 2018). "The identification of genetic mutations in ATRX, DAXX, H3.3, and more recently SMARCAL1 in ALT positive cancers has been instrumental in further defining the molecular basis of ALT." (PMID 30214690, 2018). "As an alternative to upregulation of TERT expression, cancers can also use the ALT pathway for telomere maintenance, associated with inactivating mutations in either the ATRX or DAXX genes." (PMID 29312603, 2017). "Still inside the X-chromosome cluster, there are a few cancer-related genes (ATRX, MTCP1, PHF6), but the majority of the genes should be just the results of the X-chromosome inactivation." (PMID 28198667, 2017). "To better understand the mechanism that leads to the telomerase-ALT switch in telomerase-positive cancer cells, we constructed different cell lines with specific telomeric DNA damage, ATRX knockdown, DAXX deletion or TERT KO." (PMID 27578458, 2016). "How does ATRX/DAXX repress ALT and what is the molecular basis of its activation in cancer cells with wild-type ATRX/DAXX?" (PMID 27323951, 2016). "In contrast to ATRX/DAXX, however, ASF1 is expressed in ALT cell lines and ASF1 mutations have yet to be identified in any ALT cancers." (PMID 26143912, 2015). "The Pediatric Cancer Genome Project (PCGP) conducted a study of 40 patients with metastatic neuroblastoma and found mutations in ATRX and ALK in 22% and 14% of the patients correspondingly." (PMID 25528190, 2014). "Mutations in the ATRX/DAXX complex and histone H3.3 were found to correlate with features of ALT in many cancers." (PMID 24563217, 2014). "ATRX, ARID1A, PBRM1, and SMARCA4 are also among the most frequently mutated chromatin factors in cancer, and are all components of the chromatin remodeling complex SWI/SNF, which has been shown to facilitate double-strand break repair." (PMID 25484917, 2014). "However, loss of ATRX is not the sole driver of the ALT phenotype in ULMS, as the prevalence of ALT activity (53–78%) significantly exceeds the frequency of ATRX alterations and is markedly higher than in most cancers." (PMID 40867239, 2025). "DAXX and ATRX form the histone 3.3 (H3.3) chaperone complex, which loads H3.3 into the telomeric region of the chromatin that protects the DNA from alternate lengthening of telomers, a mechanism commonly used by cancer cells." (PMID 39579056, 2025). "The involvement of factors like RAD51 and the ATRX/DAXX complex suggests that further elaboration of this pathway could provide critical insights into how ALT-positive cancers maintain their proliferative capacity." (PMID 39858038, 2025).
cancer (continued). "Our results indicated that DAXX and ATRX undergo coordinated expression changes during malignant transformation, consistent with their known role as functional partners in chromatin regulation and telomere maintenance in human cancers." (PMID 41472189, 2025). "A second X-escapee that exhibits sex-biased effects on cancer is ATRX." (PMID 38949020, 2024). "Why does the loss of ATRX/DAXX lead to ALT in cancer cells, but genetic knock-out of ATRX/DAXX does not?" (PMID 37107548, 2023). "By contrast, ATRX loss (via ATRX mutations) and TERT activation (via TERT amplification or TERTp mutations) often show mutual exclusivity in various cancers, awaiting a similar confirmation in CM by future studies concurrently analyzing both of these genes for genetic alterations." (PMID 37761808, 2023). "Emerging reports highlight the correlation between ATRX loss and the ALT process in human cancers." (PMID 37373974, 2023). "The effect of ATRX on overall survival (OS) varies by cancer type." (PMID 37200088, 2023). "Translation of these results to patients with ATRX-mutant cancers could enable genomically guided cancer therapy approaches to improve patient outcomes." (PMID 37200088, 2023). "In other studies, lack of ATRX immunolabelling due to a loss-of-function ATRX mutation was reported in 3 refractory corticotroph pituitary tumors and 4 corticotroph-carcinomas." (PMID 36917358, 2023). "A systematic analysis of the whole-genome data of 31 cancer types revealed that 22% of cancers have neither TERT expression nor ATRX mutations (8.1% of GBMs and 10.2% of LGGs)." (PMID 35953846, 2022). "Biallelic loss of ATRX has been associated with increased gwLOH in breast but not ovarian or other cancer cohorts." (PMID 35643464, 2022). "However, this increase in TIF numbers was associated with the appearance of very short telomeres (< 0.5 kb) only in the ALT‐positive ATRX‐wt cancer cell line NY." (PMID 35920001, 2022). "ATRX can promote immunogenicity and anti-cancer immunity by affecting DNA damage repair pathways." (PMID 35860239, 2022). "ATRX mutations are also often associated with the Alternative Lengthening of Telomeres (ALT) in cancers, although the loss of ATRX alone is not sufficient to trigger the ALT phenotype." (PMID 35406561, 2022). "Sequencing data from the Sanger and Broad Institutes indicated that none of these cancer cell lines displayed a mutation in ATRX or DAXX, except NOS1 that had a homozygous loss of the ATRX genes." (PMID 35920001, 2022). "Interestingly, we also identified mutations in both ATRX and PTEN associated with young adult UCEC, suggesting a pan-cancer relationship between these gene-level mutations and young adult cancer." (PMID 34788626, 2021). "Further, a subset of cancers shows extremely low TERT expression, possibly suggesting they belong to ALT through mutations outside ATRX or DAXX or to completely unknown telomere maintenance pathways." (PMID 34097189, 2021). "While mutations in ATRX are generally rare in cancers overall, with less than 1% of 84,000 cases in The Cancer Genome Atlas containing an ATRX mutation, rates of ATRX mutations in ALT cancers are comparatively much higher." (PMID 34828344, 2021). "The ATRX/ALT status could be used as a diagnostic marker and potentially a highly specific target for cancer therapy." (PMID 32984050, 2020). "Mutations in ATRX, DAXX, and H3.3 are prevalent in ALT+ cancers." (PMID 32175073, 2020). "It should also be mentioned here that somatic ATRX mutations, and to a lesser extent H3.3 and DAXX mutations, are prevalent in cancers characterized by ALT (alternative lengthening of telomeres), a HDR mechanism to maintain telomere length that is normally suppressed by ATRX." (PMID 32849845, 2020).
cancer (continued). "Additionally, ATRX was shown to be critical for the formation of senescence-induced heterochromatin foci (SAHF) that help drive cancer cells into therapy-induced senescence." (PMID 32849845, 2020). "In a few clinical studies, DAXX or DAXX/ATRX expression loss was correlated with chromosomal instability and predicted relapse in patients with low-stage cancer (i.e., stage I–III with no distant metastasis) with DNA hypomethylation regulation." (PMID 31614769, 2019). "It is unknown yet why ALT is more frequent in some cancer subtypes and how ATRX, a recently demonstrated inhibitor of ALT, acts." (PMID 31706351, 2019). "Additionally, inhibitors of the protein kinase ATR, a regulator of homologous recombination with prolonged recruitment to telomere ends in the setting of ATRX mutation, have been found to selectively induce death of ALT-positive cancer cells." (PMID 30654820, 2019). "Here, we show that cancers with somatic mutation of SMARCAL1 are ALT positive, and this represents, to our knowledge, the only other reported gene mutation associated with ALT other than ATRX and DAXX mutations." (PMID 29802247, 2018). "The frequency of tumors lacking detectable hTERT expression and mutations of ATRX/DAXX reached up to 70–80% in some cancer types like thyroid carcinoma (79.1%), kidney renal papillary cell carcinoma (70.2%), kidney cromophobe carcinoma (80%)." (PMID 29463031, 2018). "Therefore, U-251 and UW479 are the first identified human cancer cell lines that show ALT features after in vitro knockout of ATRX, a well-known and clinically relevant ALT suppressor." (PMID 30226859, 2018). "The identification of U-251 and UW479, due to their unique telomere phenotype after ATRX loss, provides a key step in the elucidation of the molecular mechanism(s) of ALT and the identification of promising therapeutic targets for ALT-positive cancers." (PMID 30226859, 2018). "Interestingly, point mutations in histone H3.3 are common events in certain cancers, indicating that the ATRX/H3.3 chromatin pathway is a key contributor to the molecular pathogenesis of particular cancers." (PMID 30087349, 2018). "Further studies will improve our understanding of how ATRX and ERBB4 mutations and AKT/mTOR signaling promote CSCNET tumorigenesis, and may be leveraged in novel anti-cancer treatment strategies." (PMID 28042953, 2017). "Telomerase-independent cancers maintain their telomeres through a homologous recombination-dependent process known as alternative lengthening of telomeres (ALT), which is associated with genomic alterations in the genes DAXX or ATRX." (PMID 29312603, 2017). "In this context, the recurrent inactivation of the ATRX tumor suppressor protein in ALT cancer samples could be exploited." (PMID 27602331, 2016). "We next asked whether this ATRX-mediated suppression of the ALT pathway is specific to U-2 OS cells or a general feature of all ALT cancers." (PMID 26143912, 2015). "First, CENP-A, which is innately overexpressed in cancer cells, associates with histone H3, and shows increased association with transcription-coupled chaperones DAXX and ATRX." (PMID 25788983, 2015). "Ultimately, the insights provided in this work have distinct diagnostic implications and suggest the possibility that targeting MDM2 or ATRX by small molecule in a combination with CDK4 inhibitor might be promising for cancer therapy." (PMID 26697514, 2015). "Mutations of DAXX, ATRX and H3.3 have also been found to be associated with telomerase-negative human cancer cells that undergo ALT." (PMID 24563217, 2014). "PARP inhibitors, already approved for the treatment of homologous recombination-deficient cancers, may exhibit enhanced therapeutic efficacy in ALT-positive tumors, especially those harboring ATRX/DAXX loss of function, due to increased reliance on recombination-mediated telomere maintenance." (PMID 41148828, 2025).
cancer (continued). "Of the 186 patients without germline P/LP variants and available cancer genomes–exomes, 41/186 patients had a somatic variant in the DNA damage response pathway (ATRX, ATM, PPM1D, POLE) and 21/186 had a variant in the MAPK-ERK pathway (BRAF, NF1, PTPN11, MAPK12)." (PMID 40072012, 2025). "This may contribute to bias toward the detection of ALT cancers with abnormal ATRX or DAXX." (PMID 41436729, 2025). "Extensive research has failed to reveal a universal second genetic factor that defines ALT cancer biology: here, we present a model whereby the second factor is not, necessarily, genetic in nature, but an environmental pressure which provides the evolutionary niche for ATRX-null cells to flourish." (PMID 39921567, 2025). "Thus, like in ATRX, KDM6A, and H3K27M, EZHIP alterations are associated with male-skewed cancers." (PMID 38949020, 2024). "In Case 3, a CDK12 variant was detected in all cells of Regions A and B; whereas, four variants in ATRX, BRCA2, PIK3CA, and PPARG were detected specifically in Region A. All four variants displayed low VAFs (0.05–0.07), indicating a late molecular event present in a small subset of cancer cells." (PMID 39766052, 2024). "In this work, we explore the role of protein trapping in ATRX-deficient cells and demonstrate that formation of DNA-protein covalent complexes (DPCCs) and/or accumulation of proteins on DNA is a fundamental driving force in both natural and artificial models of ALT-cancer." (PMID 36940725, 2023). "Interestingly, in most of these cancers, the loss of ATRX is intimately linked to the alternative lengthening of telomeres (ALT), a unique homologous recombination-based telomere maintenance mechanism that contributes to cellular immortality in cancer." (PMID 37046839, 2023). "Loss of ATRX/DAXX may be associated with telomere insertions—fragments of tandem arrays inserted into non-telomeric regions in a subset of cancers." (PMID 37046606, 2023). "Since ATRX inactivation triggers ALT, this mechanism allows the pHGG cells to extend their telomeres without the need for telomerase reverse transcriptase expression and constitutes a way to avoid death by telomere loss, allowing cancer cells for uncontrolled proliferation and cancer progression." (PMID 35382567, 2022). "In a previous study, 22% of all TCGA cancers did not express TERT or had mutations in ATRX or DAXX." (PMID 34681758, 2021). "Also, it is known that the HR factor ATRX is defective in a variety of tumors that are commonly using the alternative lengthening of telomeres (ALT) mechanism of telomere maintenance (representing around 10–15% of all cancers; Dilley and Greenberg, 2015)." (PMID 34408777, 2021). "Moreover, therapeutic strategies leveraging G4 biology in the selective targeting of ATRX-deficient cancers have not been extensively explored." (PMID 30808951, 2019). "In this study, we used telomerase-positive cancer cells (HTC75) to discover the mechanism of the telomerase-ALT switch by inducing telomere-specific DNA damage, alpha-thalassemia X-linked syndrome protein (ATRX) knockdown and deletion of death associated protein (DAXX)." (PMID 27578458, 2016). "One of the reasons might due to telomerase-positive cancer cells have functional ATRX/DAXX complex." (PMID 27578458, 2016). "These insights identify MDM2 and ATRX as new regulators controlling geroconversion, the process by which quiescent cells become senescent, and this insight may be exploited to improve the activity of CDK4i in cancer therapy." (PMID 25803170, 2015).
cancer (continued). "Each subpanel corresponds to one gene (ATRX, OLIG2, MGMT, and IDH2) and displays its expression levels in tumors (red) and normal tissues (blue) across multiple cancer types." (PMID 40282990, 2025). "Considering the overall survival results for patients harboring ATRX or DAXX genetic alterations, we focused our attention on other altered cancer-related genes in metastatic PanNETs." (PMID 41350422, 2025). "In order to maintain their telomeres and immortality, 15% of cancers utilize a telomerase-independent mechanism, the ALT pathway, and ATRX is important in suppressing this pathway." (PMID 38949020, 2024). "Furthermore, we present unexpected predictive models of several DDR deficiencies; ATRX and IDH1 deficiency in cancers of the central nervous systems (CNSs), HERC2 and CDKN2A deficiency in skin, PTEN deficiency in cancers of the CNS and uterus, and SMARCA4 deficiency in cancers of unknown primary." (PMID 36883553, 2023). "However, it remains unclear whether there is a relationship between ALT cancers and telomere insertions since the methods for analyzing ATRX/DAXX mutations in ALT cancer datasets is lacking." (PMID 37046606, 2023). "In some cases, ATRX depletion can lead to increased activity by the ALT pathway, which drives cancer cell immortalization." (PMID 36673024, 2023). "We demonstrated the functional significance of these results by showing that TOP3A overexpression in ALT cancer cells countered ATRX‐mediated ALT inhibition and that TOP3A knockdown disrupted the ALT phenotype in ATRX‐wt cells." (PMID 35920001, 2022). "The pan-cancer PCAWG dataset had a similar pattern as the FMI dataset, where both the ATRX/DAXX and RAD21 altered groups had higher telomeric content compared to WT samples." (PMID 35227290, 2022). "miR-1269a can regulate the occurrence and development of cancer by targeting downstream genes (CXCL9, SOX6, FOXO1, ATRX, RASSF9, SMAD7, HOXD10, and VASH1)." (PMID 35252180, 2022). "To extend our data to humans, we characterized the expression of MYCN, ATRX, and DAXX proteins across 12 human cancer cell lines." (PMID 32060267, 2020). "It is possible that cancer cells with ALT rely on PRC2 function, and that therefore inactivation of both ATRX and EZH2 is synthetic lethal in CRC." (PMID 27634879, 2016). "In summary, this is the first report to show that inducing telomeric DNA damage, disrupting the ATRX/DAXX complex and inhibiting telomerase activity in telomerase-positive cancer cells lead to the ALT switch." (PMID 27578458, 2016). "In our study, using overexpression of TPP1ΔOBRD and double knocking down ATRX and DAXX by shRNAs, we observed APBs and C-circles increasing during the switch from telomerase-positive cancer cells to ALT-like cells." (PMID 27578458, 2016). "Here we investigate the relationship between ATRX expression and the ALT phenotype in U-2 OS cells, which represent one of the best-characterized models for dissecting this pathway in cancer cells." (PMID 26143912, 2015).